ALDH1A1 (aldehyde dehydrogenase 1 family member A1)
Diseases named in the same sentence as ALDH1A1 in open-access papers (continued):
Sharing a sentence is not in itself a finding about the gene and the disease.
cancer (continued). "In addition, we further investigated the colocalization between ALDH1A1 and several cancer stem/progenitor markers (EpCAM, BMI1, CD13, CD24, CD90 and CD133) which have discovered recently to evaluate “stemness” in ALDH1A1-overexpressing cells in this report." (PMID 26160842, 2015). "Several reports discuss the relationship between ALDH1A1 expression level and clinicopathological findings, which may vary depending on the type of cancer present." (PMID 26160842, 2015). "Recently, ALDH1A1 could be regarded as a cancer stem cell marker in several epithelial malignancies, and the development of ALDH1A1-targeted therapy is expected." (PMID 26160842, 2015). "In this study, we investigated the relationship between ALDH1A1 and clinicopathological findings and examined whether ALDH1A1 deserves to be a cancer stem cell marker in HCC." (PMID 26160842, 2015). "ALDH1A1 (network 1), and PIR (the most differentially expressed protein) were selected for further validation based on involvement in IPA network, regulation level and known cancer association." (PMID 26317550, 2015). "To examine whether the ALDH1A1-overexpressing cells in HCC have the properties of a cancer stem or progenitor cell, we performed double-staining IHC on randomly selected HCC specimens." (PMID 26160842, 2015). "It is still controversial whether ALDH1A1 deserves to be a marker of normal tissue stem cell in liver and cancer stem cells in HCC, and there are several conflicting reports with both affirmative and negative opinions on this issue." (PMID 26160842, 2015). "ALDH1A1 was supposed to be another important ALDH isoform in many cancers." (PMID 26575197, 2015). "Recent studies have proven that ALDH1A1 plays a key role in various biological behaviors in malignant tumors, such as cell proliferation, invasion, and chemoresistance, and it is considered as one of the progenitor markers for stem cells in many different types of tumors." (PMID 24671051, 2014). "For example, high activity of ALDH1A1 and ALDH2 increases the risk of ethanol-induced cancers." (PMID 25230277, 2014). "Conversely, ALDH1A1 depletion in A2780/CP70 cells resulted in robust increase of BRACA1 protein in association with γ-H2AX induction, demonstrating altered regulation of DNA damage response and repair networks in cancer stem-like cells." (PMID 25216266, 2014). "In addition, ALDH1A1 was highly expressed in depth of invasion, especially in T3 and T4 carcinomas, which was consistent with previously reported results." (PMID 25253129, 2014). "High expression of aldehyde dehydrogenase1A1 (ALDH1A1) is observed in many organs and tumors and may identify benign and cancer stem cell populations." (PMID 24405526, 2013). "Notably, poorly differentiated PDACs displayed more abundant ALDH1A1 strongly positive cancer cells than well-differentiated PDACs did." (PMID 24194908, 2013). "Moreover, dissociated cells of engraftments created from ALDH1A1-positive cancer cells present an average of 29% ALDH1A1-negative cancer cells, indicating that the ALDH1 phenotype gives rise to heterogeneous tumors." (PMID 23767668, 2013). "Our observed percentage of cancer samples positive for ALDH1A1 was consistent with findings in other types of prostate, head-and-neck solid malignancies, but higher than the subpopulations of ALDH1A1-positive cells in bladder and lung tumors." (PMID 23767668, 2013). "Additional studies should examine whether ALDH1A1 does indeed inhibit curcumin toxicity towards cancer cells." (PMID 23095512, 2012). "Moreover, in silico results showed that meranzin hydrate may downregulate the protein expression of two cancer stemness markers, ALDH1A1 and NANOG, which was further validated by in vitro Western blot analysis." (PMID 41473403, 2026).
cancer (continued). "Among 439 cancer-free women in our study, we found inverse associations of age at first birth and the time between menarche and first birth with expression of CD44 and ALDH1A1 and positive, though marginally significant, associations of age at menarche with CD44 expression." (PMID 38577336, 2024). "Interestingly, this pharmacological inhibition determined not only a downregulation of KIF11 expression, but also a downregulation of Aldehyde Dehydrogenase 1 family member A1 (ALDH1-A1): this is a marker of cancer stem cells (CSCs) and its high expression is correlated with poor overall survival." (PMID 38939361, 2024). "Moreover, ALDH1A1 is a marker of cancer stem cells, and is involved in LSC property maintenance." (PMID 38965225, 2024). "Therefore, targeting ALDH1A1-positive cancer cells may be a promising therapeutic strategy to influence the disease course and treatment response." (PMID 36768723, 2023). "In addition, mechanistic investigations have identified that NFATc2/SOX2 coupling can upregulate ALDH1A1 expression by binding to its 5′ enhancer, attenuate oxidative stress induced by cancer drug treatment, and lead to increased resistance to chemotherapy and targeted therapy." (PMID 36651035, 2023). "Endogenously generated aldehydes are cytotoxic at high concentrations, and we questioned whether elevated erythronate might reflect an enhanced capability of ALDH1A1-overexpressing cells to alleviate the toxicity of erythrose, thereby rendering a growth advantage for cancer cells." (PMID 37893215, 2023). "In addition, ALDH1A1 also profoundly affected acetaldehyde metabolism and drug resistance in chemotherapy, suggesting that ALDH1A1 could broadly regulate biological processes in cancer." (PMID 35280765, 2022). "Therefore, co-expression of SALL4/ALDH1A1 may serve as a potential prognostic biomarker of cancer progression in these cases." (PMID 35090523, 2022). "Thus, specifically targeting ALDH1A1 could be an effective strategy to inhibit cancer stemness and disease relapse." (PMID 35884498, 2022). "Furthermore, we performed the western blot analysis of the cancer stem cell marker, ALDH1A1." (PMID 34789798, 2021). "Aldehyde dehydrogenase 1 (ALDH1A1) is a detoxifying enzyme which catalyses the oxidation of exogenous and endogenous aldehyde substrates to their corresponding carboxylic acids and is considered a marker of stem cells as well as cancer cells in different tissues including the colon." (PMID 34827887, 2021). "Aldehyde dehydrogenase isotype 1A1 (ALDH1A1) is another cancer stem cell marker that has been found to be overexpressed in highly aggressive PCa, suggesting that it might also be of interest to study in this context as a possible target for CuCl2-based therapy." (PMID 33335914, 2020). "Subsequent studies have shown that ALDH1A1 was involved in increased metastatic capability of prostate, breast, colon, ovarian, and esophageal cancer, suggesting that the activity of the enzyme also has a functional role in more differentiated cancer cells, as well as in CSCs." (PMID 35582039, 2020). "The switching from undifferentiated state to differentiated state is highly dynamic and the fate of stem-like state can be decided by ALDH1A1 expression/activity in tumor cells, suggesting that this enzyme might represent a concrete novel target for cancer treatment." (PMID 35582039, 2020). "Also, after systemically analysis of targets for different flavonoids subclasses, it can be found that targets such as MAPT, APEX1, and ALDH1A1, which were closely related with nervous system and cancer, were significantly enriched in almost all flavonoid subclasses." (PMID 30158870, 2018). "The reason for such contradiction is unclear, however it could be related to the cell origin of the cancer and degree of maturation On the other hand, IHC analysis of ALDH1A1 expression by isotype-specific antibody, such as ALDH1A1 antibody, have shown several cancer types have favorable prognoses." (PMID 26783961, 2016).
cancer (continued). "Overall, ALDH1A1-specific targeted therapy might be useful in cancer treatment." (PMID 26783961, 2016). "However, it is still controversial whether ALDH1A1 deserves to be a cancer stem cell marker in HCC and there are several conflicting reports." (PMID 26160842, 2015). "The Gepia online database revealed a significant difference in the expression of ALDH1A1 and S100A4 between ovarian normal tissues and cancer." (PMID 40093000, 2025). "Among the ALDH isoforms present in breast cancer, members of the ALDH1 family, including ALDH1A1 and ALDH1A3, contribute to cancer stemness, progression, and resistance." (PMID 40076923, 2025). "We found that CSCs expressed high levels of tumor stemness genes (PROM1, CD24, CD47, ANPEP, ALDH1A1, OLFM4, and SOX9), and demonstrated a high cancer stemness score, along with activation of the cancer driver genes EGFR and ERBB2." (PMID 39950944, 2025). "Despite the relatively smaller number of cells in the ‘CD44_high’ cluster, CD44 expression, along with other cancer stem cell marker genes such as LGR5, ALDH1A1, and FUT4, was significantly higher compared to the ‘CD44_low’ cluster." (PMID 40849307, 2025). "Specific ALDH1 isoforms, such as ALDH1A1 and ALDH1A3, are highly expressed in certain cancer cell subpopulations that exhibit stem cell-like characteristics and are resistant to chemotherapy and radiotherapy." (PMID 39781359, 2025). "ALDH1A1 and ALDH1A3 detoxify and protect cells from these and their use has become a common detoxification strategy in cancer treatment." (PMID 40708788, 2025). "In our study, GPT2 knockdown reduced the proportion of BCa stem cell subsets, suppressed cancer cell proliferation, and downregulated the CSC markers (ALDH1A1, SOX2, OCT4, and KMT1A)." (PMID 41323791, 2025). "Accumulating evidence has shown that STAT3 activation plays an important role in the growth and maintenance of GSCs by increasing the expression of major cancer stemness markers, including CD133, Sox2, Oct4, Nanog, ALDH1A1, and integrin α6." (PMID 38474197, 2024). "Expression of ALDH1A1, ALPL, ITGA6, CD44, PROM1 (CD133), LGR5, and YAP1 upregulated in the E2 and E3 phenotypes was consistent with cancer hallmarks including cell plasticity, self-renewal, and drug-tolerant persistence." (PMID 38915538, 2024). "ALDH1A1 contributes to cancer progression by promoting epithelial-to-mesenchymal transition (EMT), a process that allows cancer cells to become more invasive and metastatic." (PMID 39456547, 2024). "We analyzed data of ER+ BC patients from three large cancer datasets to assess the expression of three pluripotency markers (NANOG, SOX‐2, and OCT4), and the stem cell marker ALDH1A1." (PMID 38400679, 2024). "We also go over the importance of cancer stem cell-related gene expression patterns, specifically CD44 and ALDH1A1 expression, in therapy resistance and disease progression." (PMID 39452555, 2024). "The most active nanocomplex impact on self-renewal, cancer repopulation, therapeutic resistance, stemness gene expression, p-AKT, and ALDH1A1 activity was evaluated for unveiling its anti-stemness mechanisms." (PMID 38720782, 2024). "Extensive testing on various cancer cell types, including K562 (a leukemia cell line), mammospheres, and B16F0 melanoma cells, has revealed elevated ALDH1A1 levels in cancer stem cells (CSCs)." (PMID 38495994, 2024). "The ALDH1A1 isoform plays a pivotal role in maintaining CSC phenotype, underscoring its potential as a therapeutic target in cancer." (PMID 38893151, 2024). "Therapeutically, targeting NFE2L2-dependent expression of ALDH1A1 and ALDH1A3 offers a promising strategy to enhance the sensitivity of cancer cells to chemotherapy." (PMID 39534872, 2024). "Malignant epithelial OC spheroids and high levels of cancer stem cell (CSC) marker, such as aldehyde dehydrogenase 1 family member A1(ALDH1A1), are frequently discovered in malignant ascites of patients with extensive peritoneal metastasis of OC." (PMID 36859398, 2023).
cancer (continued). "Various studies have reported that dysregulation of some breast stem cell markers (e.g., ALDH1A1) or signaling pathways (e.g., Hippo/YAP pathway or Hedgehog signaling) relieves drug resistance in different cancers." (PMID 37953246, 2023). "Altogether, these data confirm the ability of ALDH1A1:CD63-eGFP and SRE:CD63-eGFP expression cassettes to restrict expression of the tEV reporter within the CSC-enriched subpopulation of mEER and MOC2 cancer cell lines." (PMID 36735677, 2023). "Cancer cells with high glycolysis can release a large number of exosomes containing cancer stemness markers, including ABCG2, ALDH1A1, and EpCAM." (PMID 37919747, 2023). "Among four AcAH metabolizing enzymes, upregulation of ALDH1A1 and ALDH1B1 have been reported in various cancers." (PMID 36831600, 2023). "Regarding conventional markers of cancer stem cells, CD133, CD44, KIT, and ALDH1A1 exhibited similar expression in all the tumor clusters." (PMID 35892844, 2022). "Because the levels of ALDH1A1 expressed in the injured cornea exceeded those necessary for metabolism, it has been proposed that these enzymes may contribute to corneal tissues recovery in different way such as serving as cancer stem cell markers contributing to epithelial cell hyper proliferation." (PMID 35409392, 2022). "Since conventional markers of cancer stem cells, namely CD133, CD44, KIT, and ALDH1A1, were expressed in all the tumor clusters to a similar extent, we performed cell trajectory analysis." (PMID 35892844, 2022). "Up to now, Wnt/β-catenin signaling has been considered as the key factor in regulating cancer stem cells, and masses of cancer stemness-related genes (OCT4, ALDH1A1, LGR5, CD44, c-Myc, SOX2, and so on) are regulated by Wnt/β-catenin signaling." (PMID 36319622, 2022). "ALDH1A1 is a member of the ALDH family and is highly expressed by stem cells in ovarian and other cancers." (PMID 35884498, 2022). "These pathways and the cancer stem cell markers including CD133, CD44, Oct4, SOX-2, Nanog, and ALDH1A1 maintain distinct CSC properties." (PMID 36627897, 2022). "Further, we found that the KLF4/ALDH1A1/EGF regulatory axis contributes to Cr(VI)‐induced carcinogenesis and promotes cancer cell differentiation." (PMID 36504325, 2022). "Thus, how ALDH1A1 regulates cancer stemness could involve more than one mechanism." (PMID 35884498, 2022). "The level of unsaturated fatty acids in CSCs is higher than other cancer cells, which inhibits the activities of stearoyl-COA desaturase 1 (SCD1) and acetaldehyde dehydrogenase 1A1 (ALDH1A1) in CSCs, reduces the stemness of CSCs and delays tumor formation." (PMID 36497050, 2022). "CCL2, CRIM1, COL1A1, 6A1, 6A2 participate in cell migration, invasion, or EMT and ABCG2, ALDH1A1, NES are cancer stem‐cell markers." (PMID 36305167, 2022). "Elevated ALDH1A1 levels adversely affected the overall survival in hormone-naїve patients and were observed more frequently in CRPC than in low-stage cancer." (PMID 34572930, 2021). "Using Aurora A-as7 kinase, we have identified several direct targets, including PHLDA1, LIMK2, ALDH1A1, SPOP, YBX1, and TWIST1, in cancer cells." (PMID 34066036, 2021). "ER+ BC cells grown in coculture with DLL4+-HMVECs had higher levels of gene expression of cancer stemness-related genes (CD44, ALDH1A1, KLF4, and CD36) and PKD-1, as compared to ER+ BC cells grown in monoculture." (PMID 34168243, 2021). "In detail, ALDH9H1, ALDH18A1, ALDH3A2, ALDH1A1, ALDH1B1 and ALDH2 were expressed higher than other ALDH family genes in all cancers." (PMID 34670872, 2021).
cancer (continued). "Multiple markers of the CSC phenotype (e.g., CD44, CD24, ALDH1A1, NANOG) are found to be correlated with platinum resistance in cancer patients of various types." (PMID 34645978, 2021). "The gene expression of CRC cancer stem cell markers, including SOX2, OCT4, NANOG, KLF4, ALDH1A1, and CD44, were all highly expressed in CARMA3-overexpressed cells compared to control cells." (PMID 34885061, 2021). "The genes selected included epithelial (KRT5, CDH1, EpCAM), mensenchymal (VIM, SNAI1, TWIST), stem (ALDH1A1, PROM1), breast specific (ESR1, PALB2) and other genes related to cell cycle or other cancer pathways (CCND1, CTNNB1, Ki67, etc.)." (PMID 34071445, 2021). "CSC markers ALDH1A1, CD44, BMI1, OCT4, SOX2, and CD133 and their effects on cancer stemness, metastasis, prognosis, chemo/radiotherapy resistance and recurrence have been studied in HNSCC by our group and other researchers." (PMID 34359786, 2021). "Further, cells positive for pluripotency, stemness and cancer stem cell niche markers SOX2, ALDH1A1, EPCAM, LGR5 and PORCN were also significantly expanded in Ahr-deficient lesions along the time window analyzed." (PMID 34439225, 2021). "In human cancers, ALDH1A1 and ALDH1A3 have been found to be increased and correlated with some parameters of cancer staging, the ability of cancer cells to form metastases, and the onset of resistance to chemotherapeutic drugs." (PMID 34943045, 2021). "While ALDH1A1 is expressed in GBM, it is also expressed in other cancer types according to previous reports." (PMID 34572134, 2021). "In neoplastic processes of the cervix, ALDH1A1 and OCT4 are considered to be candidates for the role of immunohistochemical markers of cancer stem cells for early detection of tumors and monitoring during treatment." (PMID 34830452, 2021). "Cancer cells utilized here showed positivity for CD44, ALDH1A1, and CK19 markers when grown on vasculature platform." (PMID 32155897, 2020). "These pathways and the cancer stem cell markers including CD133, CD44, Oct4, Sox2, Nanog, and ALDH1A1 maintain CSC properties." (PMID 35330670, 2020). "ALDH1A1 expression was positively correlated RARα with Ets1 and metalloproteinase 9 (MMP9) was one of the most important substance related to cancer invasion and metastasis." (PMID 32984354, 2020). "The expression of ALDH1A1, a CSC marker, and the cancer stemness factors including BMI1, NANOG, and octamer-binding transcription factor (OCT4) were also reduced in both AN3CA and HEC1A cells after TRIB3 silencing." (PMID 33334065, 2020). "ALDH isoforms, ALDH1A1, and ALDH3A1 are both involved in the metabolism of the cancer drug cyclophosphamide, metabolizing the active compound to a less active form and contributing to drug resistance." (PMID 32295073, 2020). "The mRNA and protein levels of the cancer stem cell markers DCLK1 and ALDH1A1 remained unchanged in both shHPGD- and shGLI1-knockdown HT-29 and Caco-2 cell-derived colonospheres, even after LTC4 stimulation, compared with their unstimulated counterparts." (PMID 32814764, 2020). "Aldehyde dehydrogenase (ALDH) isoforms, such as ALDH1A1 or ALDH1A2, have been reported as CSC markers in several cancer types." (PMID 32726929, 2020). "Multiple lines of evidence indicate that CSN6 promotes the gene expression of stemness marker aldehyde dehydrogenase 1 A1 (ALDH1A1), indicating that CSN6 expression initiates cancer stemness in CRC." (PMID 32225170, 2020). "Upon adoptive transfer of ALDH1A1-specific CD8+ T cells into xenograft-bearing immunodeficient mice, ALDHbright cells were selectively eliminated, cancer growth and metastases were inhibited, and animals’ survival were prolonged." (PMID 32391048, 2020). "Among patients with basal-like cancers, the population co-expressing both PKCλ and ALDH1A3 (43.7%; n = 87/199) was higher than that co-expressing PKCλ and ALDH1A1 (12.1%; n = 24/199)." (PMID 32658903, 2020).